CTLA4 (cytotoxic T-lymphocyte associated protein 4)
Diseases named in the same sentence as CTLA4 in open-access papers (continued):
Sharing a sentence is not in itself a finding about the gene and the disease.
infection (219 papers, 2007 to 2026). The state of being infected such as from the introduction of a foreign agent such as serum, vaccine, antigenic substance or organism. "The interference of belatacept on GBPs, Blimp-1, and CTLA-4 should also be investigated to understand individual susceptibility to infections." (PMID 40282351, 2025). "Susceptibility to infections is a common clinical symptom among CTLA4 mutation carriers, and as in the case of SLE, EBV infections or reactivations are common, leading to an increased risk of malignancy." (PMID 36405723, 2022). "To investigate the influence of the infection history as disease trigger, we compared affected and unaffected CTLA4 mutation carriers’ seroprevalence for EBV (EBNA-1) IgG, CMV IgG, parvovirus B19 IgG, HSV-1/2 IgG and Toxoplasma gondii." (PMID 36405723, 2022). "Lack of CTLA-4 transducing cytoplasmic tail increases Th2 response and disease susceptibility when compared to intact CTLA-4 transgenic mice resistant to infection and with strong Th1." (PMID 33776999, 2021). "We previously demonstrated that the antifibrotic effect of single-sex infection with female schistosomes is associated with increased CTLA-4 expression in livers of these mice." (PMID 31950032, 2019). "In consideration to S. mansoni infection in mice, it has been shown that blocking of CTLA-4 by anti-CTLA-4 antibodies leads to significant weight loss and altered Th2 response in these mice when administered during the acute stage of infection." (PMID 31950032, 2019). "With respect to murine S. mansoni infections, blocking of CTLA-4 during acute infection was associated with significant weight loss and altered type 2 cytokine responses indicating the crucial importance of this regulator during S. mansoni infection." (PMID 31950032, 2019). "For example, during infection with a more virulent P. yoelii variant, CTLA-4 blockade induced markedly increased serum levels of TNF-α accompanied by severe inflammation and reduced survival." (PMID 28894272, 2017). "In summary, we show that activation of the CTLA4 pathway is responsible for adaptive immune dysfunction, immune paresis, and infection susceptibility in patients with ALF." (PMID 28363639, 2017). "The CTLA4 gene polymorphism has been suggested to influence infection after pediatric heart transplantation." (PMID 24015180, 2013). "In this study, the risk of infection according to CTLA4 SNPs was investigated in 304 patients who received kidney graft transplants between 2008 and 2012." (PMID 24015180, 2013). "The compromised immune regulatory functions of CTLA-4 contribute to the complex infectious landscape in affected individuals, necessitating comprehensive management strategies that address both the primary immunodeficiency and associated infections." (PMID 38535602, 2024). "Mice with a primary infection of male S. mansoni also showed signs of reduced fibrosis, though not as evident as those initially infected with females, possibly due to high expression of cytotoxic T-lymphocyte-associated protein 4 (Ctla4) by Foxp3+ Tregs." (PMID 37153566, 2023). "Moreover, polymorphisms in PD-1, PD-L1, and CTLA-4 have been associated with the development of a diverse array of infections, suggesting a direct correlation between immune dysregulation and infection development." (PMID 36612078, 2022). "All together our results evidence an increased expression of CTLA4 gen in target organs from PRRSV-1-infected animals during the first 2 weeks post-infection associated with the inflammatory tissue-damage observed in the lung, particularly in Lena-infected piglets." (PMID 36713151, 2022). "Indeed, RA patients with prior exposure to TNF inhibitors were recently shown to have a greater 1-year risk of hospitalized infections compared with patients exposed to CTLA4 Ig." (PMID 28264025, 2017).
infection (continued). "The increased proportion of CTLA4-bearing cells in ALF indicates a central role for CTLA4 pathway in the predisposition to infection and that blockade of this immunosuppressive pathway may be beneficial in restoring antimicrobial responses." (PMID 28363639, 2017). "The role of CTLA4 SNPs in T cell-mediated immunity in renal transplantation and association with infection after transplantation is unknown." (PMID 24015180, 2013). "Therefore, this study was designed to investigate the associations between five CTLA4 SNPs (rs733618 C/T, rs4553808 A/G, rs5742909 C/T, rs231775 A/G, and rs3087243 G/A) and infection in Chinese kidney transplant recipients." (PMID 24015180, 2013). "Preclinical studies with PD-L1 agonists and CTLA-4 mimetics demonstrated robust plaque reduction in diabetic mouse models; however, establishing a safe and effective dose in humans remains a major barrier, particularly in elderly patients already predisposed to infection and malignancy." (PMID 41463504, 2025). "Additionally, genetic variations in immune regulatory genes encoding CTLA-4 and Blimp-1 may influence individual susceptibility to infection and immune modulation under belatacept therapy." (PMID 40282351, 2025). "Additionally, when analyzed cumulatively for all three ICI classes, there was a statistically increased risk of ICIs when a co-occurring infection was present: PD-1 inhibitors 1.91 (1.74, 2.09), PD-L1 inhibitors 2.05 (1.64, 2.55), CTLA-4 inhibitor (ipilimumab) 1.70 (1.33, 2.18)." (PMID 39199593, 2024). "In this study, we confirmed excessive amounts of CD39 and CD73 expression by PD-1-deficient Tregs in infected mice, as well as higher levels of CTLA-4 expression in conventional T cells from PD-1-deficient mice during infection, which could antagonize co-stimulatory signaling of T cells." (PMID 35666747, 2022). "In addition, the specifically down-regulated miR-145-5p in LW pigs could target Cytotoxic T-lymphocyte associated protein 4 (CTLA-4), which had a significant lower expression in TC infection group than that in LW infection group." (PMID 30353051, 2018). "The proportions of PD-1+ and CTLA-4+ cells also increased in older people with long COVID symptoms at 3m post-infection." (PMID 40416973, 2025). "It is consistent with prior observations in highly virulent PRRSV-1 Lena infections, where CTLA4 expression was upregulated to a greater extent than CD28 expression in PRRSV-infected lung, indicating an imbalance favoring IDO1 induction." (PMID 40459260, 2025). "At 6 months after infection, the number of cells expressing PD-1+, CTLA-4+ in CD4+ and CD8+ cells were higher than that at 3 months after infection; A previous study demonstrates that PD-1 expressing SARS-CoV-2 specific CD4+ T cells were exhausted." (PMID 40416973, 2025). "In contrast, Class1 was dominated by viral-infection annotations and antigen presentation (e.g., HLA-DRB1/DQB1/C, CD74, CTLA4, GZMB, PRF1), consistent with HIV-associated immune activation." (PMID 41394852, 2025). "In the case of avian coccidiosis, infection with Eimeria triggers the expansion of Tregs, which is associated with increased expression of IL-10, TGF-β, and CTLA-4." (PMID 40390138, 2025). "As evidence for recent encounter with antigen, spike-specific and SEB-reactive CD4+ and CD8+ T cells from convalescent and infection-naive patients were compared regarding their CTLA-4 expression." (PMID 38326340, 2024). "For panel 1, SAM identified a significant increase in the expression of cytotoxic T lymphocyte antigen 4 (CTLA-4) in cluster 1 at week 4 post-infection." (PMID 39411786, 2024). "We found that CTLA4+ T cells were elevated only in the mice group infected with CNA25 after 7 days of post infection and later on it reduced to basal level." (PMID 38783167, 2024). "Dialysis patients with prior infection had significantly higher spike-specific CD4+ T-cell levels with lower CTLA-4 expression compared to infection-naive patients." (PMID 38326340, 2024).
infection (continued). "In general, vaccine-induced T cells were largely polyfunctional with high CTLA-4 expression levels as sign of recent antigen encounter, which is known to increase on antigen-specific T cells during vaccinations or active infections, and decrease thereafter." (PMID 38594497, 2024). "The frequency of effector Tregs cluster 4 (CCR7+CTLA4+ICOS+CD38hi) was higher in HW+ Flores residents compared to the average of post-infection CHHIL time points (4 to 104 WPI) (P = 0.029) and decreased after deworming (P = 0.021)." (PMID 39013877, 2024). "Overall, however, we found that the estimated total infection frequency was higher in DN, PD-1+ and DP cells compared to CTLA-4+ cells." (PMID 36776833, 2023). "HeLa cells infected with Ad-Ipi were shown to express and secrete human anti-CTLA-4, as detected by Elisa and Western Blot on supernatant collected 48 hours post-infection." (PMID 37180141, 2023). "We found weak evidence for PD-1+ cells having a higher intact infection frequency compared to CTLA-4+ cells within this data (p=0.04)." (PMID 36776833, 2023). "There was also a temporal increase of CTLA-4+ DC with all infections – except for Day 30 with the only MTB-infected mice." (PMID 37965256, 2023). "Together, this indicates that cells expressing CTLA-4 have a lower infection frequency of HIV-1 genomes containing an intact nef compared to cell types that don’t express CTLA-4." (PMID 36776833, 2023). "We also found evidence for DN cells having a higher intact infection frequency compared to CTLA-4+ cells (p=0.01) and DP cells (p=0.03) within this data." (PMID 36776833, 2023). "Overall, however, we observed that CTLA-4+ cells and DP cells had the lowest estimated infection frequency per 106 cells of intact nef compared to the other cell subsets." (PMID 36776833, 2023). "Consistent with previous work, however, we found that PD-1+ cells had the highest overall estimated infection frequency per 106 cells of intact p24 gene, followed by DN cells, DP cells and CTLA-4+ cells." (PMID 36776833, 2023). "In general, we found strong evidence for PD-1+ cells having a higher intact p24 infection frequency compared to DN cells, CTLA-4+ cells and DP cells within this data (all p<0.00001)." (PMID 36776833, 2023). "Studies indicated that high expression of CTLA-4 affected the quality of T cell response function after infection with HIV and HBV." (PMID 37355637, 2023). "Overall, we observed that DN and PD-1+ cells had a higher estimated infection frequency of genetically-intact genomes compared to CTLA-4+ and DP cells." (PMID 36776833, 2023). "Mice were infected with VACV and treated with anti-CTLA4 antibody or isotype control IgG before and after infection." (PMID 37161048, 2023). "It has been shown in vitro that the HIV-1 Nef protein can downregulate CTLA-4 expression by 57-77% during productive infection." (PMID 36776833, 2023). "Regarding EM and CM T lymphocytes as CTLA-4+PD-1+ DP cells, there was a significant increase in both populations after infection, a phenotype compatible with tolerogenic functions." (PMID 35720410, 2022). "Although similar frequencies of CTLA‐4+CD4+FoxP3+ regulatory cells (TREG) were found between groups, CTLA‐4 expression in this compartment was twice as high in symptomatic compared to asymptomatic infection." (PMID 35475529, 2022). "Specifically, MAC infection triggered the upregulation of TIM-3 on CD8+ T cells and NK cells, whereas MABS infection triggered the upregulation of CTLA-4 on multiple immune subsets." (PMID 36439147, 2022). "CTLA-4 can influence infection progression and antiviral immune response (Tavakolpour, Alavian and Sali, 2016)." (PMID 37767077, 2022). "CTLA‐4+CD4+ T cells expressing high CD25 levels were also increased in symptomatic infection, but conventional CD45RA− memory CD4+ T cells became important sources of CTLA‐4 expression during asymptomatic infection compared to symptomatic counterparts." (PMID 35475529, 2022).
infection (continued). "We searched Medline (Ovid 1996–week 4 February 2021) using advanced search, for the following keywords: (“Infection” or “Infectious Disease”) and (“Immune checkpoint inhibitor” or “PD-1” or “PD-L1” or “CTLA-4”)." (PMID 34607905, 2022). "Furthermore, the increased expression of CTLA-4 and PD-1 immune checkpoint markers in T lymphocytes may explain the susceptibility of dairy cattle to infection in the prepartum and calving periods, especially when considering the importance of T cells for mucosal immunity." (PMID 35937283, 2022). "CTLA4-Ig or mouse IgG2a isotype control antibody was administered beginning on day 4 after infection to avoid inhibiting the initial priming interactions." (PMID 34206262, 2021). "In the context of infection, Plasmodium vivax infected individuals have exhausted γδ T cells with characteristically high levels of CTLA-4 among other ICRs, however, its contribution is undefined." (PMID 34572874, 2021). "Recently, it has been reported that CTLA-4 expression on Tregs inhibit the function of T follicular helper (TFH) cells and its blockade with CTLA-4 neutralizing antibody restore the ability of TFH cells to clear the infection." (PMID 34071064, 2021). "MAIT cells showed an increased expression of PD-1 and CTLA4, but Ki-67 expression changed little after infection." (PMID 32811991, 2021). "A study that collected patient samples during the 2014–2015 Ebola virus outbreak, showed that infection led to very low numbers of blood Vδ2+ cells, and that patients who survived had lower levels of surface CTLA-4 on their Vδ2+ cells." (PMID 34572874, 2021). "Neither RhCMV-specific CTL population exhibited significant changes in frequency, memory phenotype, granzyme B expression, exhaustion marker (PD-1 and CTLA-4) expression, or polyfunctionality between pre- and chronic SIVmac239 infection timepoints." (PMID 32922404, 2020). "In contrast, very low frequencies (<2.5% on average) of RhCMV-specific CTLs expressed CTLA-4 upon stimulation, both at pre- and chronic SIVmac239 infection timepoints." (PMID 32922404, 2020). "For example, a previous study showed that the number of cells expressing CTLA-4 was significantly increased in mice at 1 and 2 weeks after infection with Trichinella spiralis (as compared to controls)." (PMID 31134084, 2019). "When given early after infection, livers of CTLA-4-Ig-treated mice showed significantly reduced collagen deposition and decreased expression of profibrotic genes in comparison to controls." (PMID 31950032, 2019). "Therefore, this study does not provide a probable tool, which could be considered for therapeutic treatment in human natural infection, but contributes a puzzle piece to the effect of CTLA-4 in S. mansoni-associated fibrogenesis and its role in disease progression." (PMID 31950032, 2019). "For example, administration of the anti-CTLA-4 mAb was previously reported to enhance T-cell responses, and thereby eliminate infection by the virulent bacteria, Listeria monocytogenes." (PMID 31134084, 2019). "In a study of a BALB/C mouse model infected with L. donovani, the authors observed an increase in CTLA-4+ expression in the initial stages of infection, 24–48 hours after infection." (PMID 31506501, 2019). "These functionally exhausted T cells express high levels of inhibitory molecules such as PD-1 and CTLA-4, which are thought to contribute to the T cell dysfunction and chronicity of the infection." (PMID 29483916, 2018). "As recently shown, Ctla4 expression levels were significantly elevated after preinfection with female schistosomes in a bisexually infection system using an extended preinfection period." (PMID 29743881, 2018). "Mechanistic studies showed that cross-linking surface CTLA-4 in cultures of spleen cells taken from mice infected with a lethal infection, induced TGF-β secretion." (PMID 30631323, 2018).
infection (continued). "Another study evaluating patients during the acute phase of infection, demonstrated that survivors have T cells that express lower levels of the inhibitory molecules CTLA-4 and PD-1, compared to fatal EVD cases with high viral load." (PMID 29795572, 2018). "A trend toward a higher (but not significant) grade of rejection was seen at day 14 post-transplant after just four doses of CTLA4-Ig in mice that received all three infections compared with mock-infected mice." (PMID 29963060, 2018). "Peripheral blood samples from patients with ALF had a higher proportion of CD4+ CTLA4+ T cells than controls; patients with infections had the highest proportions." (PMID 28363639, 2017). "We found that the infection led to an increase in the expression of PD-1 and CTLA-4 in spleen CD4 T cells from infected mice at 21 days p.i. compared to control cells." (PMID 28114324, 2017). "We demonstrated that GRAIL expression during infection was modulated by the mammalian target of the rapamycin (mTOR) pathway, since addition of IL-2 or CTLA-4 blockade in splenocytes from mice 21 days post infection led to a reduction in GRAIL expression." (PMID 28114324, 2017). "Enhanced survival was mirrored by reduced fungal burden in the lung, spleen, and brain, demonstrating the potential of CTLA-4 blockade to both inhibit fungal growth at the initial site of infection and to limit potentially lethal dissemination." (PMID 27973396, 2016). "In line with this, administration of anti-CTLA-4 antibodies during infection with T. cruzi has been shown to improve CD8+ T cell-mediated immunity." (PMID 27332899, 2016). "In agreement, mice treated with a CTLA-4 blocking mAb 1 day after infection demonstrate significantly lower parasite burden by 1 month post-infection, consistent with the timing of CD8 T cell exhaustion." (PMID 26932389, 2016). "In agreement, at week 2 post-infection a reduced frequency of infiltrating CD4+ T cells expressing deactivation or suppressive molecules (CTLA4, GITR, ICOS) were seen in the lungs of pDC-depleted mice." (PMID 27992577, 2016). "C57BL/6 mice showed an increased transcriptional level of Qa1 in heart and increased levels of CTLA-4 in esophagus and PD-1 in both heart and esophagus, during the acute infection (P < 0.05), compared to controls and early chronically infected animals." (PMID 25688175, 2015). "CD69+ T cells were elevated early after infection while HLA-DR+ and CTLA4+ T cells were elevated during the recovery phase of those who survived." (PMID 24658451, 2014). "Several inhibitor molecules on CD8+ T cells have been also reported which are expressed at various time points after infection, such as CTLA-4, PD-1, TIM-3, among others." (PMID 25251060, 2014). "Then, we checked the abundance level of cytotoxic T-lymphocyte-associated protein 4 (CTLA-4) and clathrin light chain A (CLTA) by Western blot, noting that CLTA was more abundant in infected animals whereas CTLA4 showed reduced levels after infection." (PMID 24308825, 2013). "Were also determined the percentage of regulatory T cells CD4+ CD25hi which showed similar levels between infected and uninfected mice, but this population of cells was an apparent decrease in the expression of CTLA4 on the third day of infection." (PMID 22666132, 2012). "Infected animals treated with α-CTLA-4 always succumb to infection significantly earlier than animals treated with α-PD-L1." (PMID 22319445, 2012). "Nevertheless, after day 7 of infection, whole body, head and isolated brain parasite burdens were significantly higher in α-CTLA-4- and α-PD-L1-treated mice than in control mice." (PMID 22319445, 2012). "CD8+ T cells isolated on day 5 post infection from α-PD-L1 -treated mice secreted significantly more IFN-γ than did CD8+ T cells from α-CTLA-4 treated mice." (PMID 22319445, 2012). "Infection of N. americanus significantly increased the proportion of cells expressing CTLA-4 (p = 0.0002) and GITR (p<0.0001)." (PMID 22087344, 2011).